CD163 (CD163 molecule)
Diseases named in the same sentence as CD163 in open-access papers (continued):
Sharing a sentence is not in itself a finding about the gene and the disease.
melanoma (continued). "Moreover, IFNγ signatures (CXCL10, CXCL9, IDO1, IFNG, and STAT1) and myeloid lineage phenotypic and functional markers (CD14, CD163, CD33, and CD68) were also significantly increased in melanoma patients with high ETV7." (PMID 33424867, 2020). "Cluster differentiation 68 (CD68) and CD163 were positive and S100, CD1a, langerin, human melanoma black 45 (HMB-45) and Melan-A were negative in immunohistochemical staining." (PMID 32532290, 2020). "Pretreatment tumor biopsies from a total of 213 patients (158 for the training set and 55 for the validation set) treated with BRAF or BRAF/MEK inhibitors within the Italian Melanoma Intergroup were stained with selected immune markers (CD8, CD163, β-catenin, PD-L1, PD-L2)." (PMID 31730502, 2019). "In addition, TAMs are prominent in the tumor stroma in melanoma, and POSTN stimulates CD163+ macrophages to produce several specific cytokines including Treg-related chemokines [chemokine ligand 17 (CCL17), CCL22]." (PMID 29410946, 2018). "Moreover, by analyzing melanoma samples for SMA and both CD163 and CD68 expression using immunohistochemistry, we observed fibroblasts and macrophages localized together in bands of connective tissue traversing melanoma metastases taken from skin and lung." (PMID 28450382, 2017). "Notably, TAM-related chemokines, such as CXCL5, CXCL10, and CCL22, as well as a TAM-activation marker, soluble (s)CD163, could be predictive markers for efficacy and immune-related adverse events (irAEs) in anti-PD1 Abs-treated advanced melanoma patients." (PMID 34912726, 2021). "Both CD68+ve and CD163+ve TAMs were more abundant in metastatic compared to non-metastatic melanomas, and in malignant compared to benign melanocytic lesions, a finding which has been associated with tumor progression and metastasis aas well as poor clinical outcome." (PMID 34831352, 2021). "We first analyzed macrophage subsets in cryopreserved samples, using triple-color labeling with CD11c, CD209, and CD163, to quantify cells with macrophage morphology in normal skin, skin melanoma metastases, and primary melanoma tumors (non-metastasizing and metastasizing)." (PMID 34439098, 2021). "To prove our hypothesis, we performed immunohistochemical staining for POSTN and CD163 in five patients with in-transit advanced melanoma without irAEs, and in two patients with in-transit advanced melanoma with irAEs." (PMID 29643991, 2018). "Moreover, the functional characterization of CD163+ and CD204+ macrophages in oral melanocytic tumors and of Iba1+ cells in cutaneous tumors may help to deepen our knowledge of the immune pathways involved in melanoma progression and mediated by TAMs." (PMID 35937296, 2022). "Since serum sCD163 and CXCL5 are, at least in part, derived from CD163+ TAMs that are activated by periostin, and chemokine profiles from TAMs are determined by the stimulation of stromal factors, spontaneously produced TAM-related factors could be detected in serum from melanoma patients." (PMID 31080803, 2019). "Moreover, in a recent study, multispectral imaging of CD3, CD8, FOXP3, CD163, and PD-L1 was used to analyze the tumor microenvironment as a predictor of the successful generation and expansion of autologous tumor-reactive tumor infiltrating lymphocytes (TIL) in melanoma patients." (PMID 26885371, 2016). "In addition, incorporating measures of CD163+ macrophages and the CD8+:PD-L1+ ratio increased the negative predictive value of this immunoprofile, which, if validated, could be used as a predictive biomarker to guide immunotherapy in melanoma patients." (PMID 26885371, 2016). "These pockets were 20–50 μm in diameter, contained CD8+ T cells and CD163+ cells, and lacked dense collagen fibers and CD31, similar to CRATERs found in melanoma tumors." (PMID 41109214, 2025). "Occasional CD163+ TAMs that strongly express IL-10 transcripts were observed in the melanoma TME, although the vast majority of CD163+ TAMs were negative for IL-10 mRNA." (PMID 38903497, 2024).
melanoma (continued). "Surprisingly, the addition of autologous T cells inhibited expression of CD206, CD163, and CD16 in tri-cultured melanoma-conditioned macrophages irrespective of CDDO-Me treatment." (PMID 35265066, 2022). "For image quantification, we chose CD68 for macrophage segmentation because very few CD68+ cells were negative for CD115 or CD163, indicating that very few cells other than macrophages were CD68+ in melanoma tissues." (PMID 34439098, 2021). "In many melanomas, there were no CD68+ macrophages within tumours or peritumoural tissue, but there were high levels of CD163+ macrophages across almost all cases." (PMID 32843682, 2020). "The pertinent negative markers include histiocytic markers (CD163, CD14, CD1a, langerin), FDC markers (CD21, CD23, CD35, clusterin, CXCL13), hematolymphoid markers (CD45, CD3, CD20, CD79a), vascular markers (CD31, CD34), melanoma markers (melanA, SOX10, HMB45, S100), and others (ALK, CD30)." (PMID 40563703, 2025). "There was negative correlation between CD68 and CD163 mean fluorescence intensity (MFI) (R= −0.36, n = 6, p < 0.001); however, neither CD163 nor CD68 nor CD115 defined separated M1/M2 macrophage subsets, indicating that they are pan-macrophage markers in melanoma." (PMID 34439098, 2021).
COVID-19 (87 papers, 2020 to 2026). A disease caused by infection with severe acute respiratory syndrome coronavirus 2. "Inflammatory biomarkers associated with COVID-19 severity (IFNγ, and CD163) were associated with some symptoms and syndromes." (PMID 40449327, 2025). "In particular, the association between ferritin, soluble CD163, IL-18, and COVID-19 prognosis was assessed." (PMID 38398719, 2024). "The level of ACE2 expression in the lungs is positively correlated with an increased risk of severe infection and complications in COVID-19, as well as with an increase in macrophage infiltration and CD163 expression." (PMID 37109672, 2023). "A gene set analysis showed a significant similarity of CD163+ macrophages associated with COVID-19 to profibrotic macrophage populations found in idiopathic pulmonary fibrosis." (PMID 37109672, 2023). "Beyond cytokines, chemokines, and sICs, soluble CD14 (sCD14) and soluble CD163 (sCD163) as myeloid differentiation and activation markers are elevated in the plasma of COVID-19 patients and associated with immunopathology." (PMID 37676005, 2023). "Notably, the macrophage-associated state in COVID-19 was dominated by an IFN-γ response with upregulation of CD163 and HLA-DQA2, contrasting sharply with the type I/III interferon signature reported in European cohorts." (PMID 42195327, 2026). "Thus, the shift towards more mature CD163+ CD14+ DC3 in COVID-19 patients was associated with inflammation and higher disease activity." (PMID 34614036, 2021). "In our study, some markers of the intussusceptive vascular remodeling typical for COVID-19 were upregulated during the acute (Ccl12, Gdf15, and Cd163) or chronic phase (Col3a1, Cxcl12)." (PMID 40021627, 2025). "In fact, these elevated systemic CD163 levels were correlated with proinflammatory cytokine release (particularly IL-6) in COVID-19-infected patients." (PMID 39334711, 2024). "In COVID-19, analyses of damaged lung tissue revealed an increase in macrophage density with a higher proportion of CD163 positive population." (PMID 38540252, 2024). "The data of our study showed an upregulation of CD163 positive maternal macrophages and a higher PD-L1 expression in acute and post-COVID-19 male placentas." (PMID 39589546, 2024). "In opposite to PE, CD163 positive maternal macrophages are significantly upregulated in the decidua of male acute COVID-19 placentas." (PMID 39589546, 2024). "In the contrary, CD163-positive macrophages are significantly upregulated in male COVID-19 placentas, whereas there is only a trend for such upregulation in female placentas from infected placentas compared with the uninfected negative controls." (PMID 39589546, 2024). "In COVID-19 patients, abnormal activation of macrophages expressing M1/M2 polarization markers (CD68, CD80, CD163, and CD206) in the lung is associated with the production of cytokines, including IL-6, IL-10, and TNF-α, as indicated by previous studies." (PMID 39100091, 2024). "There was a trend to a significant upregulation of CD163 (p = 0.063) between control macrophages and acute COVID-19 macrophages in the decidua of placentas of female origin." (PMID 39589546, 2024). "The macrophage population upregulated CD163 in COVID-19 lungs compared to controls, and showed an enrichment of CCL18 expression in later disease phases compared to the acute lungs." (PMID 36774347, 2023). "More importantly, MAFB knockdown led to a significant downregulation of the gene sets that define the pathogenic SPP1+ MØ (GSE145926), MoAM3 (GSE155249), or CD163+/LGMN+ MØ (accession number EGAS00001005634) subsets in severe COVID-19." (PMID 37917179, 2023). "Single nuclei RNA sequencing (snRNAseq) data obtained from some of the same samples and donors 23 confirmed that CD163+ macrophages in COVID-19 are the cellular source of CCL18." (PMID 36774347, 2023).
COVID-19 (continued). "The clinical significance of the activation of CD163+ macrophages is demonstrated by increased levels of soluble CD163 (sCD163) in the blood plasma of patients with COVID-19." (PMID 37109672, 2023). "We observed that both PBMCs and monocytes had upregulated expression of mRNAs of myeloid markers, including CD14, α-integrins (CD11b and CD11c), FCγ receptors (CD64A), and macrophage scavenger receptors (CD163), as a function of the severity of COVID-19." (PMID 37310504, 2023). "CD163-expressing monocyte-derived macrophages accumulate in the lungs of patients with COVID-19 acute respiratory distress syndrome (ARDS) and are associated with profibrotic responses and pulmonary fibrosis." (PMID 37369668, 2023). "In this study, we demonstrate that CD163+ macrophages accumulating in COVID-19 lungs produce CCL18 and spatially allocate this chemokine to the fibrotic patches." (PMID 36774347, 2023). "Overall, PCA of classical monocytes revealed an acute-phase COVID-19 clustering pattern upon bacterial challenge, which was strongly associated with low expression of HLA-DR, CD86, CD80 and a high expression of CD163, CX3CR1 and CD11b." (PMID 35007290, 2022). "Peripheral blood monocytes isolated from patients affected by COVID-19 related pneumonia exhibited an increased expression of CD163 as well." (PMID 35741108, 2022). "Recent studies found low CD169/Siglec1 and high CD163 expression on circulating monocytes in severe COVID-19 patients." (PMID 35326463, 2022). "Consistent with the specific expression of macrophage signature genes, the numbers of CD163+ macrophages were higher in COVID-19 skin lesions relative to CLE." (PMID 35045565, 2022). "Whereas uninfected lung tissue contains a predominant CD163+ macrophage population that is negative for the other lineage markers, we observed increased density of CD4+CD163+ macrophages in the COVID-19 cases with ALI." (PMID 35446789, 2022). "Upon bacterial challenge, classical monocytes from COVID-19 patients (acute- and rec-phase) displayed high expression of CD163 and CD11b, but low expression of the activation markers HLA-DR, CD86 and CD80." (PMID 35007290, 2022). "Other potential mechanisms involved the ribosome and COVID-19 pathways; the inflammatory factors genes, such as Ccl17, Cxcl17, Cd163, Cxcr5, and Il31ra, and the lncRNAs genes; and the respiratory cilia functions." (PMID 36072401, 2022). "They confirmed an increase in monocyte inflammation marker (sCD14), neutrophil inflammation marker (MPO), and soluble CD163 (sCD163) in patients with severe COVID-19." (PMID 35563874, 2022). "Quantitative IHC analysis demonstrated that patients with COVID-19 had significantly higher mean intensities of CD163 (8.5 ± 2.20 vs. 26.3 ± 1.15, P = < 0.0001) and CD61 (0.28 ± 0.04 vs. 10 ± 0.78, P = < 0.0001) staining than those without." (PMID 35260724, 2022). "Monocytes from severe COVID-19 patients displayed decreased HLA-DRA and increased CD163 expression compared to healthy donors and mild COVID-19 patients, consistent with prior reports." (PMID 36466858, 2022). "As well as the macrophage-related genes MYD88 and STAT1, were upregulated in bronchoalveolar cells from patients with mild COVID-19, while cells from patients with severe COVID-19 were characterized by upregulation of the CD163 marker of M2 macrophages." (PMID 34225749, 2021). "Next, we compared expression of markers associated with cell activation (CD40), maturation (CD16), homing (CXCR6), tissue recruitment (CD62L), and polarization (CD163) on monocytes and DC subsets in young and aged COVID-19 patients relative to healthy donors." (PMID 34707619, 2021). "We observed a significantly increased frequency of CD163+ CD14+ cells and decreased frequency of CD163+ CD14– cells in the DC3 subset in COVID-19 patients compared to controls." (PMID 34614036, 2021).
COVID-19 (continued). "We observed a shift towards a more mature CD163+ CD14+ phenotype within the DC3 subset in acute COVID-19 correlating with disease severity and inflammatory markers." (PMID 34614036, 2021). "It is still unclear, however, if the CD163+ CD14+ phenotype of DC3 in the blood of COVID-19 patients contributes to or is a byproduct of the inflammatory response." (PMID 34614036, 2021). "Correlating with systemic inflammation and expansion of activated Tfh and B cells, DC3 from COVID-19 patients contained more CD163+ CD14+ cells." (PMID 34614036, 2021). "We report an increased frequency of monocytes expressing CD62L and CD163 in the blood from both young and aged COVID-19 patients." (PMID 34707619, 2021). "Accordingly, increased sCD163 was observed in COVID-19 patients, and a potential pathophysiological association between CD163+ macrophages and COVID-19-associated cytokine storm has recently been proposed by RNA-seq transcriptome analyses." (PMID 34966385, 2021). "Levels of monocytes expressing CD62L and CD163 in both young and aged COVID-19 patients were significantly higher compared to healthy donors." (PMID 34707619, 2021). "In our analysis, CD86 gene expression decreases and CD163 increases in CD16+ monocytes in severe cases of COVID-19 compared to healthy controls." (PMID 34108966, 2021). "In addition, in COVID-19 blood monocytes display an activated phenotype (i.e., CD11b/CD16/CD66bhigh), and CD163/CD206low monocytes are decreased in severe compared to mild COVID-19, also suggesting a more activated phenotype." (PMID 40710346, 2025). "Biological analysis revealed significant associations between certain PACS symptoms and biomarkers of viral activation (IFNγ, IP-10), COVID-19 severity (CD163) and vascular activation (VCAM-1, ICAM-1), mainly in subjects whose symptoms had lasted less than a year." (PMID 40449327, 2025). "There is a low abundance of CD163 in the post-COVID-19 male and female decidua." (PMID 39589546, 2024). "Moreover, more and darker-stained macrophages (brownish-yellow of on CD163 staining) were detected in the COVID-19 tissues than in the controls." (PMID 38882332, 2024). "We also see an increase of CD163+ macrophages in islets of COVID-19 samples, which could be an indication of fibrogenic monocyte infiltration." (PMID 39232561, 2024). "We identify alveolar myeloid subsets with transcriptional profiles that differ from other lung diseases as well as several subsets with similar transcriptional profiles as reported in healthy participants (Metallothionein) or patients with COVID-19 (CD163/LGMN)." (PMID 37978185, 2023). "Adding to a possible role of CD163 in proinflammatory macrophage activation, alveolar spaces of severely infected COVID-19 lungs contained a large amount of CD163+ macrophages as a sign of altered airway macrophage populations and correlating with diffuse alveolar damage and worse patient outcomes." (PMID 35163309, 2022). "Other potential mechanisms of the RC decoction against the ALI involved the pathways of ribosome and coronavirus disease 2019 (COVID-19); the target genes of inflammatory factors, such as Ccl17, Cxcl17, Cd163, Cxcr5, and Il31ra, and lncRNAs; and the regulations of the respiratory cilia." (PMID 36072401, 2022). "Moreover, the serum levels of soluble CD163, as a marker of macrophage activation, were enhanced in COVID-19 patients." (PMID 35163309, 2022). "While increased CD38 expression across monocyte subsets was a general feature unrelated to disease severity, higher levels of CCR2 on iMonos, as well as lower levels of HLA-DR and CD86 with increased expression of CD163 in all monocyte subsets, were found in severe COVID-19." (PMID 33479167, 2021). "We, therefore, hypothesized that the CD163+ CD14+ fraction within DC3 is also expanded in COVID-19 patients." (PMID 34614036, 2021).